CD4 (CD4 molecule)
Diseases named in the same sentence as CD4 in open-access papers (continued):
Sharing a sentence is not in itself a finding about the gene and the disease.
cryptosporidiosis (continued). "The severity of cryptosporidiosis depends on the extent of immunosuppression, as indicated by the CD4+ T count." (PMID 37858196, 2023). "In cryptosporidiosis, the principal immune response is cellular immunity mediated by the CD4+ cells that triggers IFN-γ production in response to Cryptosporidium spp." (PMID 36355894, 2022). "Cryptosporidiosis was more commonly found in subjects with CD4+ < 200 cells/μL and who had a higher viral load (p > 0.05)." (PMID 36355894, 2022). "Rashmi and Kumar49 suggested a correlation between Cryptosporidium infection inHIV-seropositive patients and their CD4+ cell count." (PMID 32037854, 2020). "The results of themeta-analysis on the dependent variable of cryptosporidiosis were related to theindependent variable number of CD4+ T-lymphocyte." (PMID 32037854, 2020). "Antiretroviral therapy is still one of the therapeutic interventions that showed aremarkable effect on cryptosporidiosis in HIV-seropositive patients because it leadsto the recovery of CD4+ counts." (PMID 32037854, 2020). "Cell-mediated responses, especially interferon gamma (IFN-γ) production by CD4+ T cells, are well described in individuals with prior cryptosporidiosis." (PMID 31131855, 2020). "Cell mediated immunity, particularly CD4+ T cells, is essential for the protective immune response to Cryptosporidium infection." (PMID 28800747, 2017). "Chronic cryptosporidiosis generally occurs in patients with CD4 counts below 200 cells/cumm, and patients with CD4 count below 50 cells/cumm suffer from severe infections." (PMID 26981284, 2016). "Patients with a CD4 T cell count < 200 cells/μl had a similar rate of any intestinal parasitic infection or cryptosporidiosis compared to those with counts ≥ 200 cells/μl, but with some type of diarrhea." (PMID 27165271, 2016). "In fact, several studies have documented a correlation between CD4 count <200 cells/cumm and symptomatic cryptosporidiosis, in HIV patients." (PMID 26981284, 2016). "Both animal and human studies confirmed that CD4+ Th1 response against cryptosporidiosis is mediated mainly by IFN-γ and is MHC II-dependent." (PMID 22685452, 2012). "Moreover, CD4+ T cells are important for the immune response to Cryptosporidium infection in both human and murine models." (PMID 37858196, 2023). "Only two subjects had CD4+ < 100 cells/μL, both of which were found positive for cryptosporidiosis." (PMID 36355894, 2022). "A case report showed that subclinical cryptosporidiosis could be found in individuals with CD4+ < 100 cells/μL." (PMID 36355894, 2022). "Since CXCL10 increases the rate of HIV replication in vitro, elevated CXCL10 in cryptosporidiosis may contribute to enhanced destruction of CD4+ T cells due to HIV infection." (PMID 36504775, 2022). "Similarly, in the present meta-analysis, we showed that the patients with low CD4 counts had a higher prevalence rate of Cryptosporidium infection (p < 0.0001)." (PMID 32351207, 2020). "The symptomatic improvement in patients seems to be more a function of the improved CD4 T lymphocyte count rather than a decrease in viral load, and intestinal mucosal CD4 cell numbers increase before both a rise in circulating CD4 lymphocytes and a decrease in Cryptosporidium infection." (PMID 22685452, 2012). "Our study indicated that having diarrhea and having less than 200 CD4 cells μL, in HIV-infected patients, increase the risk of infection by Cryptosporidium, whereas using antiretroviral therapy in HIV-infected patients meaningfully decreases the risk of cryptosporidiosis." (PMID 32351207, 2020). "However, as is the case with many cryptosporidiosis studies, there are substantial differences in clinical manifestations between infected individuals, and even patients with very low CD4+ counts may only exhibit transient diarrhea." (PMID 22685452, 2012). "Thus, CD4+ T-cells appear to play a dominant protective function in cryptosporidium infection." (PMID 22685452, 2012).
cryptosporidiosis (continued). "In accordance, CD4+ and CD8+ T cells are shown to be essential immune mediators in response to cryptosporidiosis and in its recovery in calves." (PMID 38318169, 2024). "Two important immune mediators in response and recovery from cryptosporidiosis are IFN-γ production and CD4+ cells." (PMID 37325809, 2023). "The use of 500 mg of paromomycin, 3 to 4 times daily for a minimum of 14 days showed an exceptional cure rate of cryptosporidiosis, particularly in HIV-infected adults with CD4 >200 cells/uL, and not in severely compromised HIV patients." (PMID 34562754, 2021). "Although the cell-mediated immune response to cryptosporidiosis is known to be via CD4+ T cells, the role of CD8+ T cells is not yet clear." (PMID 37858196, 2023). "Although CD4+ T cells and IFN-γ are known to be essential for the clearance of Cryptosporidium infection, CD8+ T cells and humoral responses might also be involved." (PMID 37858196, 2023). "In this study, the patients’ mean CD4+ T-cell count was 81.66 ± 98.36 cells/mm3 while the median was 50, which is consistent with the previous reports stating that HIV-infected patients can have Cryptosporidium infection even when they are on HAART." (PMID 36851577, 2023). "Many studies in animals and humans, however, have demonstrated the roles of cell-mediated responses (CD4+ and CD8+ cells) and humoral immune responses, such as IgA, IgG, IgM, and protection against cryptosporidiosis conferred by hyperimmune colostrum (25, –, 28)." (PMID 35735982, 2022). "In contrast, CD4 counts of RT patients, with and without cryptosporidiosis, were comparable (290 ± 23.6 cells/cumm versus 326 ± 15 cells/cumm, P = 0.269)." (PMID 26981284, 2016). "The current study also emphasizes the importance of screening HIV-infected patients for Cryptosporidium infection; with the priority given to patients with diarrhea as well as to those with a CD4 count < 200 cells/μl regardless of their diarrheal status." (PMID 27165271, 2016). "The current study shows that CD4 count was less in HIV patients with Cryptosporidium infection than without." (PMID 26981284, 2016). "CD4 count of HIV-infected patients with cryptosporidiosis was lower than those without (95 ± 11.3 cells/cumm versus 169 ± 13.7 cells/cumm, P = 0.002)." (PMID 26981284, 2016). "Immunocompromised (both HIV and RT) patients with cryptosporidiosis had lower CD4 count than noninfected ones (mean ± SD: 214 ± 162 cells/cumm versus 260 ± 144 cells/cumm, P = 0.041)." (PMID 26981284, 2016). "Triple infection 1 (4.5%), double infections 1 (4.5%) and 3 (13.6%) for Microsporidium & Cyclospora and Cyclospora & Cryptosporidium infections respectively, and no single Cyclospora infection was observed among patients with CD4+ cell count between 200-499 cells/mm3." (PMID 30369995, 2018). "Similarly, difference in rate of Cryptosporidium infection by diarrhea status was statistically significant in patients with a CD4 level < 200 cells/μl (no diarrhea 15 %, acute diarrhea 6 %, chronic diarrhea 28.3 %; χ2 = 9.12, df = 2, P = 0.01)." (PMID 27165271, 2016). "Adoptive transfer of CD4+ IELs (nonconventional lymphocytes located among the epithelial cells in the lumen) cells in SCID mice reduces parasite load and confers better protection against Cryptosporidium infections than CD8+ IELs." (PMID 37325809, 2023). "Maternal HIV infection did not appear strongly related to Cryptosporidium infection in our study and this may be explained in part because the majority of HIV-positive women were otherwise healthy and not severely immunocompromised based on their CD4 cell counts." (PMID 25275519, 2014).
enteropathy (33 papers, 2010 to 2025). "HIV enteropathy includes pronounced gut-associated CD4+ T-cell loss and an impaired gastrointestinal (GI) epithelial barrier." (PMID 38773400, 2024). "One of the hallmarks of HIV disease is a rapid and profound depletion of CD4 cells in the gut-associated lymphoid tissue, resulting in an enteropathy with increased translocation of microbial products, despite ART." (PMID 37206666, 2023). "Cell death and loss of CD4+ T-cell subsets critical for gut health contribute to mucosal inflammation and enteropathy, which weaken the mucosal barrier, leading to microbial translocation, a major driver of IA/INFL." (PMID 34367156, 2021). "Interleukin (IL)-4 production by CD4+ T cells was measured as a causative factor of enteropathy, and anti-IL-4 antibody was used to reveal the role of Foxp3+ OVA-specific Tregs (aiTreg) in this process." (PMID 28234975, 2017). "HIV enteropathy includes pronounced CD4+ T-cell loss, increased intestinal permeability, and microbial translocation that promotes systemic immune activation, which is implicated in disease progression." (PMID 23101545, 2012). "This animal model reproduced a CD4+ T cell-mediated enteropathy, defined as hyperplasic-infiltrative (type II), similar to that described in CD patients." (PMID 30405050, 2018). "This procedure can induce a CD4+ T cell-mediated enteropathy, defined as hyperplasic-infiltrative (type II), resembling that described in CD patients." (PMID 30405050, 2018). "We previously showed that EW-fed RAG-2 deficient OVA23-3 mice, in which nearly 100% of CD4+ T-cells are OVA-specific, developed a similar enteropathy to that of the OVA23-3 mice in the current study." (PMID 25290461, 2014). "The inflammatory CD4+ T-cell functions in GALT and the maintenance of persistent CD4+ T-cell responses to dietary OVA in MLNs suggest that MLNs promote the development of enteropathy in OVA23-3 mice during EW-diet feeding." (PMID 25290461, 2014). "HIV enteropathy generally occurs in advanced disease (e.g., CD4+ T-cell count <200 cells/μl) and is characterized by changes in villous morphology, absorption, and mucosal permeability." (PMID 25266928, 2014). "In the enteropathy model, the changes in CD4+ T cells were also accompanied by an increase in CD4+/Foxp3+ (Tregs) cells, which suggests the development of a counter-regulatory response, as previously reported." (PMID 22348021, 2012). "Similar results were found in a mouse model capable of reproducing a CD4+ T-cell-mediated enteropathy in the presence of gliadin, where colonization by B. longum CECT 7347 strain increased levels of IL-10 and reduced CD4+ T cells, counteracting the effects of gliadin." (PMID 38396767, 2024). "One of the hallmarks of HIV infection is a rapid and profound depletion of CD4+ T-cells in the gut-associated lymphoid tissue (GALT), resulting in an enteropathy with an increased translocation of microbial products, including inflammatory bacterial endotoxin, despite ART." (PMID 37206666, 2023). "Furthermore, in the gliadin-induced enteropathy animal model, this strain has been shown to reduce the peripheral CD4+ T cells, rise IL-10, and shrink TNF-α production." (PMID 31013929, 2019). "A group of Japanese researchers noted that CD4+CD25+CD127low T cells isolated from IPEX (Immune dysregulation, Polyendocrinopathy, Enteropathy, X-linked) patients also exhibited appreciable suppressive activity, although less than that exhibited by Treg cells from healthy controls." (PMID 28553653, 2017). "Our study also demonstrated that IFN-γ sensitisation, prior to gliadin administration, was necessary to induce an enteropathy mediated by CD4+ T cells, while IFN-γ sensitisation alone did not cause significant changes in lymphocyte subpopulations." (PMID 22348021, 2012).
enteropathy (continued). "Recently, Foxp3- CD4+CD25+CD127- iTreg with appreciable suppressive activity on effector T cell proliferation, although less than that displayed by Treg cells from healthy controls, were demonstrated in patients with immune dysregulation, polyendocrinopathy, enteropathy, X-linked (IPEX) syndrome." (PMID 22905732, 2012). "Previous studies have focused on faecal calprotectin as a biomarker of enteropathy, which is typically elevated in HIV-positive compared to HIV-negative individuals and progressively increases with a reduction in CD4+ T cell count (Hestviket al., 2012)." (PMID 33336080, 2020). "In Group 2 macaques with severe enteropathy, counts of CD8+IFN-γ+ and CD4+IFN-γ+ T cells were elevated also prior to treatment." (PMID 30050538, 2018). "Continued feeding of the EW diet until day 28 enabled the OVA23-3 and R23-3 mice to recover from the enteropathy, with a decrease in the excessive IL-4 production by OVA-specific CD4+ T cells and with an increase in the percentage of aiTregs." (PMID 28234975, 2017). "A study of HIV enteropathy showed a concordant increase in i-FABP2 and duodenal helper T cells (CD4+)." (PMID 27824883, 2016). "Although aiTregs suppress the proliferation of T cells, they may not easily inhibit the IL-4 production of OVA-specific CD4+ T cells, and aiTregs might be reprogrammed to Th2 cells themselves in a T-cell-dependent manner and aggravate enteropathy." (PMID 28234975, 2017). "A gut biopsy of patient 3 showed subtotal villous atrophy of the duodenum as Marsh IIIb enteropathy with no CD20+ B cells and moderate to high amounts of CD3+, CD4+, and CD8+ intraepithelial cells compared with noncarriers." (PMID 37943617, 2024).
neurosyphilis (33 papers, 2004 to 2025). Infection of the brain or spinal cord by Treponema pallidum. "When we considered only patients with CSF VDRL positive titers as having confirmed neurosyphilis, results were maintained and CD4 count ≤ 350 cells/mm3also appeared as a risk factor." (PMID 40157281, 2025). "The studies had several limitations: small sample size, different diagnostic criteria for neurosyphilis, inconsistent exposure to cART, missing peripheral CD4 counts, and HIV RNA levels." (PMID 35819944, 2022). "A study in Taiwan, China, showed that CD4 T lymphocyte counts (CD4 cell counts) ≤200 cells/μL was associated with failure of neurosyphilis treatment." (PMID 34678871, 2021). "The rate of ocular and neurological involvement is higher in patients with HIV infection and a CD4 count of <350/μl is associated with an increased risk of neurosyphilis." (PMID 21235811, 2011). "Likewise 24.6% of HIV positive patients were reported to have neurosyphilis in a study done in Canada and development of neurosyphilis was significantly associated with CD4 less than 500 cells/μl and uncontrolled viremia." (PMID 33276749, 2020). "In conclusion, our study showed a correlation between VDRL titers, HIV viral load, CD4 count and neurological symptoms with the diagnosis of neurosyphilis." (PMID 40157281, 2025). "VDRL titers ≥ 1:32, HIV viral load ≤ 400 copies/mm3 and CD4 count ≤ 350 cells/mm3 were independent factors for neurosyphilis diagnosis." (PMID 40157281, 2025). "Our findings are in accordance with other recent studies which have shown that CD4+ count and serum VDRL titers, among other factors, were risk factors to neurosyphilis diagnosis in the HIV-infected population." (PMID 40157281, 2025). "For the case vignette with a CD4+ cell count above 350 cells/mm3, 75.8% of respondents indicated neurosyphilis treatment; when CD4+ cell count was below 350 cells/mm3, this percentage was 88.4%." (PMID 36043668, 2023). "Assessment of cerebrospinal fluid (CSF) abnormalities in neurosyphilis patients without human immunodeficiency virus (HIV) infection indicated that CD3+ CD4+ T cells play a dominant role in the CSF of neurosyphilis patients." (PMID 34917045, 2021). "LncRNA-ENST00000421645 was significantly differentially expressed with a very low false discovery rate (FDR) in peripheral blood CD4+ T cells of neurosyphilis patients and healthy subjects." (PMID 34917045, 2021). "The number of CD4+ T cells in the CSF of asymptomatic neurosyphilis patients and neurosyphilis patients with brain parenchymal injury was significantly higher than that in the CSF of syphilis patients without nerve injury." (PMID 34917045, 2021). "A previous study observes that 2258 lncRNAs are dysregulated in CD4+ T cells derived from neurosyphilis patients compared to controls, and an enrichment analysis revealed these lncRNAs T cell receptors, MAPK, and TGF-β signaling pathways." (PMID 32547537, 2020). "By contrast, the odds of symptomatic neurosyphilis correlate negatively with an increased blood CD4+ T lymphocytes count." (PMID 32331231, 2020). "A high index of suspicion for neurosyphilis should be maintained in HIV-infected patients presenting with ocular symptoms even if they are compliant with retroviral therapy with good CD4 cell counts." (PMID 31011497, 2019). "This study reveals the differential expression profiles of lncRNAs in the CD4+ T cell response to the T. pallidum infection in neurosyphilis patients." (PMID 29167762, 2017). "The mRNA and lncRNA expression profiles of CD4+ T cells that were isolated from neurosyphilis patients and healthy controls were analyzed by microarray." (PMID 29167762, 2017). "Neurosyphilis in HIV-positive patients was related to CD4 ≤ 350 cells/ml, serum RPR titer ≥ 1:32, male gender, and an HIV viral load (VL) above 10000 copies/mL12,17–19." (PMID 29133821, 2017).